SLC35B3 (solute carrier family 35 member B3)
Description:
Probably functions as a 3'-phosphoadenylyl sulfate:adenosine 3',5'-bisphosphate antiporter at the Golgi membranes. Mediates the transport from the cytosol into the lumen of the Golgi of 3'-phosphoadenylyl sulfate/adenosine 3'-phospho 5'-phosphosulfate (PAPS), a universal sulfuryl donor for sulfation events that take place in that compartment.
Synonyms: C6orf196; PAPST2; CGI-19; dJ453H5.1
Tractability: Antibody: UniProt predicts a signal peptide or a membrane-spanning region. PROTAC: its protein half-life has been measured.
Gene: Protein-coding gene on chromosome 6 (8,411,435 to 8,435,983, reverse strand). Ensembl gene ENSG00000124786.
Subcellular location: Golgi apparatus membrane
Pathways (Reactome):
Metabolism: Transport and metabolism of PAPS
Transport of small molecules: Transport of nucleotide sugars
Gene Ontology:
Molecular function: 3'-phosphoadenosine 5'-phosphosulfate transmembrane transporter activity
Biological process: 3'-phosphoadenosine 5'-phosphosulfate transport; 5'-adenylyl sulfate transmembrane transport; 3'-phospho-5'-adenylyl sulfate transmembrane transport; transmembrane transport
Cellular component: Golgi membrane
Genetic constraint (gnomAD): Loss-of-function variants: 14 observed, 19.23 expected, observed/expected ratio (o/e) 0.73, 90% interval 0.48 to 1.14. The upper end of that interval is the gene's LOEUF score, 1.14, which puts it in group 4 of 6, group 1 being the genes least tolerant of losing a copy. Missense variants: 212 observed, 259.71 expected, observed/expected ratio (o/e) 0.82, 90% interval 0.73 to 0.92. Synonymous variants: 75 observed, 85.83 expected, observed/expected ratio (o/e) 0.87, 90% interval 0.72 to 1.06.
Homologues: Orthologues: chimpanzee SLC35B3 (99% identical), macaque SLC35B3 (95% identical), pig SLC35B3 (95% identical), dog SLC35B3 (95% identical), rabbit SLC35B3 (93% identical), rat Slc35b3 (92% identical), mouse Slc35b3 (91% identical), guinea pig SLC35B3 (89% identical), tropical clawed frog slc35b3 (85% identical), zebrafish slc35b3 (83% identical), Drosophila melanogaster Papst2 (55% identical), Caenorhabditis elegans pst-2 (48% identical). Paralogues in human: SLC35B1 (24% identical), SLC35B2 (23% identical), SLC35B4 (22% identical).
Diseases named in the same sentence as SLC35B3 in open-access papers:
SLC35B3 is named in the same sentence as 6 diseases in open-access papers, as found by Europe PMC text mining. Sharing a sentence is not in itself a finding about the gene and the disease. The quoted sentences say what the papers report.
colitis (2 papers, 2024 to 2025). Inflammation of the colon. "Mechanistically, IAA upregulated the expression of key molecules 3’-phosphoadenosine 5’-phosphosulfate synthase 2 (Papss2) and solute carrier family 35 member B3 (Slc35b3) involved in mucin sulfation via AHR, thereby enhancing intestinal barrier function and ameliorating colitis." (PMID 39068517, 2024).
colorectal cancer (1 paper, 2022). A primary or metastatic malignant neoplasm that affects the colon or rectum. "However, SLC35B3—a paralog of SLC35B2—is expressed in the colon and might compensate for the loss of SLC35B2 activity in colorectal cancer." (PMID 35798875, 2022).
schizophrenia (1 paper, 2021). A major psychotic disorder characterized by abnormalities in the perception or expression of reality. "We also report the following modules of unknown relevance to schizophrenia: Glucuronidation with FDR= 8.81E−04 (genes UGT1A3 to UGT1A10) and Phase II - Conjugation of compounds with FDR= 5E−03 (SLC35B3, GGT7, MGST3, and UGT1A3 to UGT1A10)." (PMID 33892787, 2021).
lip (1 paper, 2025). "Novel loci include those mapping to LHX8 and TSBP1 (combined clefts), ARHGEF18 and ARHGEF19 (cleft lip with/without palate), FBN2 (cleft lip only), SLC35B3 (cleft palate only), CASC20 (Pierre Robin Sequence) and CHRM2 (non-syndromic cleft palate only)." (PMID 41075272, 2025).
SLC35B3 also shares sentences with these, for which no sentence is quoted: cleft lip (1 paper); cleft palate (1).